TMEM45A (transmembrane protein 45A)
Synonyms: DERP7; DNAPTP4; FLJ10134
Tractability: Small molecule: a structure with a bound ligand is known. Antibody: UniProt predicts a signal peptide or a membrane-spanning region. PROTAC: ubiquitination databases record sites on it.
Gene: Protein-coding gene on chromosome 3 (100,492,219 to 100,579,281, forward strand). Ensembl gene ENSG00000181458.
Subcellular location: Membrane
Subcellular location (Human Protein Atlas): Endoplasmic reticulum; Vesicles
Gene Ontology:
Molecular function: protein binding
Cellular component: membrane
Genetic constraint (gnomAD): Loss-of-function variants: 25 observed, 32.67 expected, observed/expected ratio (o/e) 0.77, 90% interval 0.56 to 1.07. The upper end of that interval is the gene's LOEUF score, 1.07, which puts it in group 4 of 6, group 1 being the genes least tolerant of losing a copy. Missense variants: 302 observed, 341.42 expected, observed/expected ratio (o/e) 0.88, 90% interval 0.8 to 0.97. Synonymous variants: 122 observed, 120.75 expected, observed/expected ratio (o/e) 1.01, 90% interval 0.87 to 1.17.
Homologues: Orthologues: chimpanzee TMEM45A (100% identical), dog TMEM45A (78% identical), rabbit TMEM45A (78% identical), guinea pig TMEM45A (77% identical), macaque TMEM45A (77% identical), pig TMEM45A (70% identical), mouse Tmem45a (65% identical), rat Tmem45a (60% identical), tropical clawed frog tmem45a (53% identical), rat Tmem45a2 (51% identical), mouse Tmem45a2 (49% identical), zebrafish tmem45a (47% identical). Paralogues in human: TMEM45B (44% identical), TEDDM1 (24% identical).
Diseases named in the same sentence as TMEM45A in open-access papers:
TMEM45A is named in the same sentence as 40 diseases in open-access papers, as found by Europe PMC text mining. Sharing a sentence is not in itself a finding about the gene and the disease. The quoted sentences say what the papers report.
breast carcinoma (14 papers, 2012 to 2025). "High expression of TMEM45A is linked to poorer overall survival (OS) in breast cancer, particularly in ER+ breast cancer." (PMID 39910045, 2025). "TMEM45A has been reported to be associated with chemotherapy resistance in human breast cancer and HCC cells under hypoxic conditions." (PMID 34819088, 2021). "TMEM45A has been proposed as a potential classifier of ccRCC15, but was also associated with chemoresistance in human breast cancer cells and in human hepatoma cells in hypoxic condition." (PMID 31801939, 2019). "Kaplan Meier curve showed an association between high TMEM45A expression and poor prognostic in breast cancer patients." (PMID 22954140, 2012). "TMEM45A, a transmembrane protein, which has been proposed as a biomarker of clear cell renal cell carcinoma (ccRCC), was also reported to be associated with chemoresistance in breast cancer and HCC cells." (PMID 36589233, 2022). "We demonstrate that TMEM45A is highly expressed in palbociclib-resistant breast cancer (BRCA) cells, correlating with enhanced tumor progression." (PMID 39910045, 2025). "Pan-cancer analysis of TCGA data has shown that TMEM45A is highly expressed in several cancers, including breast cancer." (PMID 39910045, 2025). "In summary, our study has identified the TMEM45A/AKT/mTOR axis as a mediator of palbociclib resistance in breast cancer by promoting glycolysis and EMT in BRCA cells, highlighting its potential as a therapeutic target." (PMID 39910045, 2025). "Previous study has found that TMEM45A plays a crucial role in hypoxia-induced breast cancer and liver cancer chemotherapy resistance." (PMID 32190895, 2020). "In the cases of breast cancer and cervical lesions, a higher expression level of TMEM45A has been correlated with a lower patient overall survival suggesting that TMEM45A is a potential biomarker for aggressiveness of breast cancer and cervical lesions." (PMID 30574087, 2018). "Recent profiling study using whole transcriptome analysis identified gene TMEM45A to be involved in hypoxia-induced resistance to taxol in breast cancer cells." (PMID 26291454, 2015). "Our findings suggest that TMEM45A may be a potential therapeutic target for overcoming palbociclib resistance in HR+ breast cancer." (PMID 39910045, 2025). "A high expression level of TMEM45A was found in the breast cancer and cervical lesions and correlated with a lower overall survival for the patient, indicating TMEM45A as a potential biomarker for the aggressiveness of breast cancer and cervical lesions." (PMID 37367036, 2023). "In the cases of breast cancer and cervical lesions, higher expression level of TMEM45A has been correlated with lower patient overall survival, suggesting that TMEM45A could be a potential biomarker for aggressiveness." (PMID 31801939, 2019). "TMEM45A expression was increased both in MDA-MB-231 human breast cancer cells and in HepG2 human hepatoma cells in conditions where protection of cells against apoptosis induced by chemotherapeutic agents was observed, i.e. under hypoxia in the presence of taxol or etoposide." (PMID 22954140, 2012). "Therefore, we speculate that TMEM45A is a mechanism of acquired resistance in breast cancer patients by activating the AKT/mTOR signaling pathway and enhancing glycolysis." (PMID 39910045, 2025). "Collectively, our findings suggest that TMEM45A may be a therapeutic target for overcoming palbociclib resistance, and exosomal siRNA delivery could be a viable strategy for precision medicine in HR+ breast cancer." (PMID 39910045, 2025). "Furthermore, high TMEM45A expression is connected to distant metastasis in breast cancer." (PMID 39910045, 2025). "We found that TMEM45A is highly expressed in cells resistant to CDK4/6i, promoting the invasive ability of breast cancer cells." (PMID 39910045, 2025). "As expected, the CCK-8 assay showed that the knockdown of TMEM45A and SHCBP1 in MDAMB468 similarly inhibited the proliferation of breast cancer cells." (PMID 38035071, 2023).
breast carcinoma (continued). "We further investigated the impact of TMEM45A and SHCBP1 knockdown on the functionality of breast cancer cells through CCK-8 and colony formation assays to determine their effects on BRCA cell proliferation." (PMID 38035071, 2023). "We conducted a search on the DepMap Portal to assess the expression levels of TMEM45A and SHCBP1 in various breast cancer cell lines." (PMID 38035071, 2023). "TCGA and GEO data analyses revealed that TMEM45A and SHCBP1 were highly expressed in breast cancer." (PMID 38035071, 2023). "Therefore, we knocked down TMEM45A and SHCBP1 and further investigated the role of TMEM45A and SHCBP1 in MDA-MB-468 breast cancer cells in vitro." (PMID 38035071, 2023). "To investigate the role of TMEM45A in breast cancer, we established BRCA cell lines with TMEM45A knockdown using siRNA targeting TMEM45A (siTMEM45A) and a negative control siRNA (siNC)." (PMID 39910045, 2025).
ovarian carcinoma (8 papers, 2018 to 2025). A malignant neoplasm originating from the surface ovarian epithelium. "Studies have indicated that high expression of TMEM45A is associated with poor prognosis in patients with breast, bladder, and ovarian cancer." (PMID 39910045, 2025). "TMEM45A is implicated in cell proliferation, migration, and invasion of different cancers like glioma (U251 and U373 cells) and ovarian cancer (HO-8910 and A2780 cells)." (PMID 30574087, 2018). "In addition, an association between TMEM45A and the regulation of TGF-β in ovarian cancer is suggested because the knockdown of TMEM45A significantly decreased the levels of the TGF-β1, TGF-β2, RhoA, and ROCK2 proteins that participate in the signaling pathway of TGF-β signaling." (PMID 37936608, 2023). "TMEM45A affects the proliferation and invasion of human ovarian cancer cells and human glioma cells." (PMID 39910045, 2025). "In ovarian cancer, it was reported that TMEM45A knockdown decrease cell proliferation, adhesion, and invasion." (PMID 37936608, 2023). "It was reported that in ovarian cancer cells, TMEM45A promotes cell proliferation by favoring the G1/S cell cycle transition." (PMID 37936608, 2023). "TMEM45A affects proliferation and invasion in human ovarian cancer cells and in human glioma cells." (PMID 31801939, 2019). "Multiple TMEM family members, such as TMEM45a and TMEM49, have been reported to contribute to progression of ovarian cancer, highlighting the potential importance of this family in tumorigenesis of ovarian cancer." (PMID 33731124, 2021). "In the context of ovarian cancer, TMEM45A protein expression has been positively correlated to TGF-β signaling pathway and this data could explain the impact of TMEM45A invalidation in this cancer." (PMID 30574087, 2018). "The absence of TMEM45A also led to a significant decrease in cell proliferation as already shown in human ovarian cancer cells and in human glioma cells, indicating that at least in four different cancer types, cell proliferation is a pathway dependent on TMEM45A expression." (PMID 31801939, 2019).
hepatocellular carcinoma (7 papers, 2012 to 2024). A malignant tumor that arises from hepatocytes. "TMEM45A has been closely associated with chemoresistance in hepatocellular carcinoma." (PMID 37561335, 2024). "Circ_TMEM45A is one of the highly expressed circRNAs in hepatocellular carcinoma and is bountifully present in serum exosomes as well." (PMID 35055115, 2022). "In order to further confirm the role of TMEM45A in drug resistance, we used another experimental model: HepG2 hepatocellular carcinoma cells exposed to etoposide." (PMID 22954140, 2012). "It has been shown that TMEM45A is involved in the process of chemoresistance in breast and hepatocellular carcinoma; however, the mechanism of this protection remains unclear." (PMID 38850316, 2024). "Thus, circ_TMEM45A may interact with other potential target proteins and unidentified miRNAs, rather than miR-665, to fulfill its oncogenic role in hepatocellular carcinomas." (PMID 35055115, 2022). "Five genes (PSRC1, SOCS2, TMEM45A, CCT5, and STC2) were selected from the TCGA training dataset to construct the prognostic CSGscore signature, which could precisely predict the prognosis of hepatocellular carcinoma patients both in the training and validation datasets." (PMID 36589233, 2022).
liver cancer (4 papers, 2012 to 2024). An epithelial or non-epithelial malignant neoplasm that arises from the liver. "TMEM45A, for instance, is overexpressed in various cancers, including ovarian, kidney, and liver cancers." (PMID 37561335, 2024). "Evidence showed that high levels of TMEM45A expression in breast and liver cancer cells may be indicative of potential resistance to cancer therapy, making TMEM45A a tumor-promoting factor." (PMID 37404478, 2023).
colorectal cancer (3 papers, 2021 to 2023). A primary or metastatic malignant neoplasm that affects the colon or rectum. "In colorectal cancer, TMEM45A is associated with multidrug resistance (MDR)." (PMID 37936608, 2023). "Some TMEM proteins have also been reported to favor epithelial-mesenchymal transition (EMT), such as TMEM45A in colorectal cancer." (PMID 37936608, 2023). "TMEM45A gene knockdown has been found to be effective in inhibiting multidrug resistance and suppressing EMT by inhibiting the TGF-β signaling pathway in human colorectal cancer cells." (PMID 34819088, 2021).
atrial fibrillation (2 papers, 2025). A disorder characterized by an electrocardiographic finding of a supraventricular arrhythmia characterized by the replacement of consistent P waves by rapid oscillations or fibrillatory waves that vary in size, shape and timing and are accompanied by an irregular ventricular response. "In relation to CV disease, TMEM45A has been upregulated in atrial tissue from patients with atrial fibrillation (AF)." (PMID 41462954, 2025).
lung carcinoma (2 papers, 2019 to 2023). "The expression of TMEM48 and TMEM97 are potential prognostic biomarkers for lung cancer, while TMEM45A and TMEM205 are implicated in tumor growth and invasion." (PMID 38248651, 2023).
renal carcinoma (2 papers, 2019 to 2024). A carcinoma arising from the epithelium of the renal parenchyma or the renal pelvis. "Some proteins of this family are potentially useful for classifying cancer grade in renal cancers (e.g., TMEM45A, TMEM116, TMEM207, TMEM213)." (PMID 38974022, 2024). "The effect of TMEM45A inactivation was investigated on responses to cisplatin in head and neck and renal cancer cells in normoxic and hypoxic conditions." (PMID 31801939, 2019). "TMEM45A was upregulated in patients diagnosed for head and neck or renal cancer." (PMID 31801939, 2019).
renal cell carcinoma (2 papers, 2019 to 2021). "In this work, the messenger RNA expression of TMEM45A was assessed in head and neck squamous cell carcinoma (HNSCC) and renal cell carcinoma (RCC) biopsies." (PMID 31801939, 2019).
actinic keratosis (1 paper, 2016). A precancerous lesion of the skin composed of atypical keratinocytes. "Whereas the expression of TMEM45A is poorly affected by inflammatory cytokines, it is upregulated in two pathological situations: psoriasis and actinic keratosis, both characterized by an abnormal and incomplete keratinization." (PMID 26785122, 2016).
breast tumors (1 paper, 2012). "We observed that high TMEM45A expression in primary breast tumors present a higher risk of cancer recurrence." (PMID 22954140, 2012).
cervical cancer (1 paper, 2023). A primary or metastatic malignant neoplasm involving the cervix. "TMEM45A knockdown reversed the cisplatin resistance of HPV-positive cervical cancer cells by increasing apoptosis." (PMID 37936608, 2023). "TMEM45A expression has also been reported to be upregulated in CaSki (+HPV 16), SiHa (+HPV 16), and HeLa (+HPV 18) cervical cancer cells, compared to the C33A cell line from HPV-negative cervical cancer with the HcerEpic normal cervical epithelial cell line." (PMID 37936608, 2023). "Furthermore, CaSki cells having the highest HPV copy number demonstrated the highest expression of TMEM45A, and SiHa cells with the lowest HPV copy number had lower TMEM45A levels, suggesting that HPV copy number may have an effect on the expression of TMEM45A in cervical cancer cells." (PMID 37936608, 2023).
corneal disorder (1 paper, 2026). A non-neoplastic or neoplastic disorder that affects the cornea. "TMEM45A directly binds prolyl-4-hydroxylase (P4HA1) to modulate extracellular matrix (ECM) synthesis, thereby contributing to fibrosis and corneal disorders." (PMID 41959721, 2026).
Fanconi anemia complementation group A (1 paper, 2019). Fanconi anemia complementation group A is a protein which in humans is encoded by the FANCA gene. "Indeed, the decrease in proliferation observed in TMEM45A-inactivated cells may be explained by the deregulation of the expression of genes implicated in G2/M transition pathway such as FANCA (Fanconi Anemia Complementation Group A) and ARPP19 (CAMP Regulated Phosphoprotein 19)." (PMID 31801939, 2019).
fibrosis (1 paper, 2025). the formation of excess fibrous connective tissue in an organ or tissue in a reparative or reactive process. "Furthermore, TMEM45A-induced cardiac fibrosis was demonstrated to contribute to AF development both in vivo and in vitro." (PMID 40102753, 2025). "Identifying TMEM45A’s ligand and elucidating the complete signaling pathway affecting cardiac fibrosis may pave the way for future research." (PMID 40102753, 2025).
glioblastoma (1 paper, 2023). The most malignant astrocytic tumor (WHO grade IV). "For example, in glioblastoma cells TMEM45A promoting cell proliferation, migration, and invasion and TMEM98 in gastric cancer, among others." (PMID 37936608, 2023). "The knockdown of TMEM45A expression by CRISPR/Cas9 in glioblastoma cell lines A172 and U251 significantly decreased cell proliferation, migration, and invasion." (PMID 37936608, 2023). "In glioblastoma cells the expression of TMEM45A favored the expression of NF-κB." (PMID 37936608, 2023). "On the other hand, the silencing of NF-κB counteracted the proliferation of the cells that overexpress TMEM45A, these data suggest that in glioblastoma cells, TMEM45A could have an oncogenic role through regulation of NF-κB." (PMID 37936608, 2023).
Hyperkeratosis (1 paper, 2021). Hyperkeratosis is a histopathological term defining a thickened stratum corneum and may be present in many different skin conditions, with many possible overlaps. "The overlapping DEGs included genes associated with hyperkeratosis (upregulated LCE3E and TMEM45A), wound healing (upregulated KRT17, IL36G, TNC, and TGFBI), barrier defects (downregulated FRAS1 and BCL11A), and response to infection (upregulated IL36G, ADAP2, DFNA5, RFTN1, LITAF, and TMEM173)." (PMID 34506598, 2021).
lung adenocarcinoma (1 paper, 2021). A carcinoma that arises from the lung and is characterized by the presence of malignant glandular epithelial cells. "Our current study is to first to report the increased cell-surface expression of TMEM45A protein in patient-derived lung adenocarcinoma samples using CyTOF." (PMID 35008313, 2021). "Our single-cell results are the first to demonstrate TMEM45A expression in human lung adenocarcinoma, which was verified by immunohistochemistry." (PMID 35008313, 2021). "The CyTOF showed the ITH of human primary lung adenocarcinoma for 14 markers; particularly, the higher expressions of GLUT1, MCT4, CA9, TMEM45A, and CD66 were associated with the lung-tumor tissue." (PMID 35008313, 2021). "Our IHC results showed the sporadic staining of HIF-1α (+) but prevalent TMEM45A staining (+++) in all 17 human lung adenocarcinoma tissues." (PMID 35008313, 2021). "Additionally, our results are the first to show TMEM45A expression in human lung adenocarcinoma, which was verified by immunohistochemistry." (PMID 35008313, 2021). "The expression of TMEM45A in lung adenocarcinoma was demonstrated through IHC of 17 patients." (PMID 35008313, 2021). "Additionally, we analyzed the ITH of human primary lung adenocarcinoma for 14 markers and are the first to report TMEM45A expression in lung adenocarcinoma." (PMID 35008313, 2021). "Our results also show, for the first time, that TMEM45A is expressed in lung adenocarcinoma." (PMID 35008313, 2021). "Our report is the first to describe the expression of TMEM45A in human lung adenocarcinoma versus nontumorous lung tissue." (PMID 35008313, 2021). "In our IHC results, the expression of TMEM45A protein in lung adenocarcinoma was not exclusively reliant on HIF-α induction." (PMID 35008313, 2021).
metastatic tumor (1 paper, 2025). "Within this list of genes in the metastatic tumor dataset, individual genes such as TMEM45A, IGFBP1, IGFBP5, and MALAT1 appeared to be associated with a worse patient survival." (PMID 40241258, 2025).
ovarian tumors (1 paper, 2018). "To further validate their possible contribution to OC mesenchymal subtype, we found that both CXCR7 and CXCL11 strongly correlate with genes associated with ECM and OC invasion, such as PRRX1, TMEM45A, and CTSK, when analyzed in the mesenchymal counterpart of ovarian tumors." (PMID 30051594, 2018).
renal fibrosis (1 paper, 2025). A final common manifestation of a wide variety of chronic kidney diseases characterized by glomerulosclerosis and tubulointerstitial fibrosis. "Previous study has demonstrated that TMEM45A was involved in the pathology of renal fibrosis." (PMID 40102753, 2025).